ISG15 (ISG15 ubiquitin like modifier)
Diseases named in the same sentence as ISG15 in open-access papers (continued):
Sharing a sentence is not in itself a finding about the gene and the disease.
tumor (continued). "Expression of ISG15 was linked to resistance to cisplatin treatment in tumor cells, suggesting ISG15 is a biomarker for drug sensitivity which is consistent with our data showing increased ISG15 and induced cisplatin sensitivity in RSK2 knockout cells." (PMID 36684450, 2022). "The protein coded by ISG15 (interferon-stimulated gene 15 ubiquitin-like modifier) was implicated in autophagy, exosome secretion, DNA repair, and immune modulation pathways; it is also a known tumor promoter by suppressing immune cell tumor infiltration." (PMID 36077244, 2022). "Additionally, ISG15 mRNA association with MMPs indicates the role in tumour progression as they have the ability to reorganise the extracellular matrix and prepare the microenvironment to produce cytokines that enhance cancer cell migration and proliferation." (PMID 33073304, 2021). "Specific soluble factors within the pancreatic TME have been found to regulate CSCs including Nodal/Activin secretion from pancreatic stellate cells, cationic antimicrobial peptide 18/LL-37 from immune cells, and IFN-stimulated factor 15 (ISG15) from tumor associated macrophages." (PMID 28692661, 2017). "Moreover, high ISG15 level was associated with more tumor recurrence and indicated a shorter overall survival and disease-free survival in NPC patients." (PMID 26919245, 2016). "Like other innate immune/stress response mediators, appropriately regulated ISG15 expression is associated with a tumor suppressor function, whereas the perturbation of ISG15 regulation is correlated with enhanced tumor progression and leads to aberrant cell signaling and malignant transformation." (PMID 25238261, 2014). "This compartmentalisation of ISG15 may reflect tumour-associated nuclear functions of ISG15 or the presence of ISGylated cellular proteins in the nucleus." (PMID 16641915, 2006). "Western blotting revealed a tumour-associated expression of ISG15 protein." (PMID 16641915, 2006). "In addition, we demonstrated that ISG15 is associated with tumor immune infiltration and may impact immunotherapy across pan-cancer." (PMID 40208307, 2025). "Therefore, it is essential to elucidate not only the multitude of cellular processes in cancer immunogenicity in which ISG15 and ISGylation are implicated but also the communication between tumor cells and their microenvironment for the improvement of the efficacy of cancer therapies." (PMID 36319753, 2022). "However, the role of ISG15 in tumor-associated macrophages (TAMs) remains poorly understood." (PMID 33424843, 2020). "Since ISG15 siRNA can silence both free ISG15 as well as conjugated form of ISG15, it remains unclear whether ISG15 siRNA-mediated suppression of tumor growth observed in these studies is causally related to the suppression of free ISG15 and/or ISG15 conjugates." (PMID 25749047, 2015). "Furthermore, under this cut-off level, clear associations could be seen between ISG15 expression and both tumour size and grading." (PMID 18627608, 2008). "Functional assays illustrate that SEMA6A overexpression exerts anti-tumor effects both in vitro and in vivo, while integrated RNA-seq and proteomic analyses identify ISG15 as a key downstream effector negatively regulated by SEMA6A." (PMID 42303907, 2026). "Collectively, these findings highlight the potential of SEMA6A as a dual therapeutic strategy in CRC: inhibiting cancer progression while enhancing anti-tumor immunity by targeting the ISG15/TGF-β1 axis." (PMID 42303907, 2026). "Isg15 belongs to the interferon-stimulated gene family, which exerts anti-tumor functions in tumor immunity." (PMID 39979981, 2025).
tumor (continued). "We further evaluated the correlation between ISG15 expression and tumor immune cell infiltration across pan-cancer, and noticeable positive correlations were observed in STAD, BLCA, LUAD, and LUSC." (PMID 40208307, 2025). "ISG15 and ISGylation affect the response of tumor cells to the immune system by affecting antigen presentation and immune cell activity." (PMID 41193953, 2025). "Up to now, in vivo studies on ISGylation in tumor occurrence are relatively scarce, thus understanding the role of ISG15 in tumor development is of great importance." (PMID 40208307, 2025). "The consistent enrichment of ISG15 across different tumor subtypes underscores the activation of interferon-mediated pathways as a conserved feature of EC5,suggesting its potential utility as a biomarker for endothelial-driven immune modulation in BC." (PMID 41394809, 2025). "Terminal deoxynucleotidyltransferase‐mediated dUTP‐biotin nick end labeling (TUNEL) and hematoxylin‐eosin staining (H&E) staining demonstrated an increased proportion of apoptotic cells in tumor tissues from Isg15 KO mice." (PMID 40126377, 2025). "Analysis of 369 HCC and 160 non‐tumor samples from the GEPIA database demonstrated a significant upregulation of ISG15 in HCC tissues." (PMID 40126377, 2025). "The tumor microenvironment was affected and the development and metastasis of tumors were promoted by ISG15 through specific signal transduction pathways." (PMID 40821990, 2025). "ISG15, a highly expressed following Type I IFN stimulation protein in this pathway, is implicated in creating an immunosuppressive tumor microenvironment (TME) and developing as immune adjuvant therapy using ISG15 targeting." (PMID 40260261, 2025). "Elevated ISG15 expression has been shown to inhibit the activity of cytotoxic T lymphocytes and natural killer cells, thereby facilitating tumor growth and invasion." (PMID 40208307, 2025). "ISG15 knockdown can reduce the tumor invasion of Foxp3+ regulatory T cells and produce a synergistic effect with anti-PD-1 antibody treatment." (PMID 41193953, 2025). "Our correlation analysis of ISG15 expression with various tumor functional statuses, performed on the CancerSEA website, revealed substantial correlations with most tumor functional statuses." (PMID 40208307, 2025). "We explored the relationship between ISG15, infiltrating immune cells, and stromal cells in the tumor microenvironment." (PMID 40208307, 2025). "In diethylnitrosamine‐induced HCC mouse model, HFD‐feeding promotes HCC progression in wildtype mice, while tumor growth is significantly suppressed accompanied by apoptosis of HCC cells in Isg15‐KO mice." (PMID 40126377, 2025). "We further investigated the expression of ISG15 by scRNA‐seq which was performed to tumour or normal bowel samples of patients with ICI treatment from our cohort." (PMID 39934971, 2025). "Since ISG15 has demonstrated both tumor-suppressing as well as tumor-promoting properties even within the same tumor type, complex mechanistic interplays between ISG15 and other immunologic factors are likely involved in immune response against cancer cells." (PMID 40936712, 2025). "Firstly, ISG15 exhibits varying expression patterns and functions across different tumor types, necessitating further clarification of its role in specific tumor types and molecular subtypes to enhance its diagnostic precision." (PMID 41193953, 2025). "Second, depletion of endogenous PRDM6 by siRNA knockdown induced the expression of anti-tumor ISGs, ISG15 and IFITM1." (PMID 40936897, 2025).
tumor (continued). "In glioma and anaplastic thyroid carcinoma (ATC), ISG15 inhibits the ubiquitination and degradation of key molecules by ISGylation to activate the expression of downstream stemness genes and enhance tumor stemness characteristics and drug resistance." (PMID 41193953, 2025). "In contrast, tumor-associated macrophage (TAM)-rich neighborhoods (C02) showed downregulation of IFN-α/β signaling genes (e.g., IFITM3, OAS1-3, MX1, ISG15), suggesting potential immunosuppression." (PMID 41138165, 2025). "Post-treatment tumor analysis confirmed coordinated downregulation of ISG15 and HMGCR proteins, aligning with in vitro findings." (PMID 41366470, 2025). "The function of ISG15 expression in the apoptotic phenotype of tumor cells is dependent on multiple factors." (PMID 41193953, 2025). "The primary and metastatic tumour tissues from these mice had very high levels of ISG15 and its ISGylation products." (PMID 38939897, 2024). "The comparison of H-score of ISG15 expression between tumor and adjacent normal tissues showed that ISG15 expression was significantly higher in PC tissues (p<0.001)." (PMID 38385083, 2024). "This elevated expression of ISG15 and ISGylation resulted in the release of high levels of vesicles with oncogenic proteins contributing to aggressive tumour progression and metastasis." (PMID 38939897, 2024). "We first analyzed data from the TCGA database to compare the ISG15 mRNA level among tumor tissues and adjacent normal tissues from patients with nine types of cancer." (PMID 38443596, 2024). "ISG15 functions in tumor development, tumor aggressiveness, cell self-renewal, and cell-to-cell communication in the tumor microenvironment, suggesting that ISG15 is an active player in cancer pathogenesis rather than a passive observer." (PMID 38443596, 2024). "The multifaceted functions of ISG15 extend beyond intracellular processes to extracellular cytokine signalling, influencing immune response, chemotaxis, and anti-tumour effects." (PMID 38400136, 2024). "Recent literature demonstrates differing and mixed expression levels of free ISG15 and ISG15 conjugates in various human tumours." (PMID 38939897, 2024). "As a therapeutic target in cancer treatment, ISG15 exhibits a double-edged nature, promoting or suppressing oncogenesis depending on the tumour context." (PMID 38400136, 2024). "The different tumour types, ISG15 target proteins, ISG15 form (conjugated/free intracellular), and its effect (protumour/antitumour) are indicated." (PMID 38400136, 2024). "We found that the expression level of ISG15 was significantly higher in PC tissues than in non-tumor tissues." (PMID 38385083, 2024). "ISG15, a ubiquitin-like molecule, which is involved in the occurrence and development of tumors and is closely related to tumor prognosis." (PMID 38644421, 2024). "Of potential clinical importance, elevated expression of ISG15 in the TME has been linked to higher histological grade, larger tumor size, a “stemmy” cancer phenotype, low CD8+ TIL content, expression of PD-L1/IDO-1/LAG-3, and poor clinical prognosis." (PMID 38312842, 2024). "We next conducted immunocytochemistry analysis to detect ISG15, Ki67 and apoptosis in tumor-derived paraffin-embedded sections, leading us to find that the tumor proliferation rate, reflected by Ki67-positive cells, was reduced by ISG15 deprivation." (PMID 38385083, 2024).
tumor (continued). "The pathway activation and tumor-cell EMT induced by ISG15 were blocked by either knockdown of RAGE expression or pharmacological inhibition of RAGE function." (PMID 38926796, 2024). "To compare the expression level of ISG15 between PC tissues and non-tumor tissues, we examined the Gene Expression Omnibus (GEO) database and excavated the data from two mRNA expression profiles (GSE16515 and GSE62452)." (PMID 38385083, 2024). "The average tumor size was significantly reduced in the ISG15-sh2+PBS group compared with the control group." (PMID 38385083, 2024). "The aim of this study is to provide molecular insights related to ISG15‐mediated EV secretion in the tumour microenvironment of malignant ascites to identify novel treatment and monitoring strategies in HGSOC." (PMID 38939897, 2024). "We observed that cotreatment with ADU-S100 + anti-ISG15 antibody resulted in improved control of B16 tumor growth vs. treatment with ADU-S100 monotherapy." (PMID 38312842, 2024). "Mechanistically, type I interferons directly reprogram tumor cell metabolism by activating oxidative phosphorylation for ATP production in an ISG15-dependent manner." (PMID 38982116, 2024). "More importantly, the NF-κB and STAT3 activation and tumor-cell EMT in peri-necroptotic microenvironment were all significantly abolished upon necroptotic-ISG15 knockdown or RAGE inhibition." (PMID 38926796, 2024). "The ISG15/ISGylation system can be oncogenic or have tumor suppressor activity depending on the tissue affected, cancer stage, and specific cancer-related alterations in signalling pathways." (PMID 37025175, 2023). "And this inhibition was significantly greater than the difference previously observed in nude mice, which indicated that ISG15 plays a critical role in activating the immune system to exert its tumor-suppressing effects." (PMID 37217923, 2023). "The results elucidated that the patients with high expression of ISG15 showed positive staining for Granzyme B and Perforin, indicating that the lymphocytes had stronger killing effect on tumor cells." (PMID 37217923, 2023). "Our work demonstrates the anti-tumor efficacy of a Listeria-based vaccine targeting ISG15, designated Lm-LLO-ISG15, in an immunocompetent CRC murine model." (PMID 36831577, 2023). "We demonstrated, for the first time, as a proof of concept, that vaccination against ISG15 with Lm-LLO-ISG15 significantly controlled the CRC tumor burden in both subcutaneous and orthotopic syngeneic CRC mouse models." (PMID 36831577, 2023). "The correlation between ISG15 expression and tumor stem cells and malignant progression of ATC was analyzed by single-cell RNA sequence from the Gene Expression Omnibus." (PMID 37501099, 2023). "In nasopharyngeal carcinoma cells, the expression of ISG15 upregulated the cancer stem cell phenotypes, such as pluripotency, tumorigenicity, and tumor-sphere formation." (PMID 36674743, 2023). "CD4+ T cells isolated from tumor tissue downregulate granzymes B and H and upregulate genes associated with regulatory T cells (FOXP3, IKZF4, CD38, ISG15)." (PMID 37648263, 2023). "In the cancer setting, extracellular ISG15 acts as an immune adjuvant to enhance antigen specific CD8+ T cell tumor immunity, increasing their production of IFNγ." (PMID 36911698, 2023). "This suggests a trend towards apoptosis in the cells of the Lv-ISG15 group in tumour cells co-cultured with PBMC." (PMID 37217923, 2023). "Human macrophage cluster 5 highly expressed the most signatures of mouse Isg15+ macrophages and specially appeared in the tumor group." (PMID 37483625, 2023). "In this review, we have discussed studies that highlight a role of ISG15 as a key element in aging and age-associated CVD beyond its classical roles in the defense against pathogens and as a tumor suppressor." (PMID 37025175, 2023). "Collectively, we demonstrated that therapeutic vaccination with Lm-LLO-ISG15 induced an effective ISG15-specific anti-tumor response mediated by T cells." (PMID 36831577, 2023).
tumor (continued). "The effects of ISG15 on tumor cells and T lymphocytes were assessed using RT-qPCR and Western Blot and in vivo experiments." (PMID 37217923, 2023). "At the end of the experiments, the weight of tumor tissues in ISG15-knockdown mice was significantly less than that in control group." (PMID 37501099, 2023). "ISG15 in several cancer types of cervix, blood, and ovaries decreases proliferation and increases apoptosis, resulting in tumor suppression." (PMID 36319753, 2022). "The IFN pathway was induced by APR-246 in vivo, as evidenced by the increased ISG-15 staining in tumours." (PMID 36138076, 2022). "Of the six genes identified, IFI27, IFI6, IFITM1, ISG15, and BST2 have been reported to be associated with cancer cell proliferation and tumor growth." (PMID 35267998, 2022). "Tumor cell-secreted ISG15, which acts as a tumor microenvironmental factor, induces an M2-like phenotype, promoting tumor progression and suppression of cytotoxic T lymphocyte response." (PMID 35159348, 2022). "Compared with normal tissues, the expression of ISG15 was significantly increased in tumor tissues, whereas the expression of ZFP36 was significantly decreased." (PMID 35538543, 2022). "Because of these apparently contradictory functions, ISG15 has been designated as a “double-edged sword” in tumour development; however, our data suggest that ISG15 has a pro-tumoral role in SFT." (PMID 35864381, 2022). "Given that ISG15 is significantly induced by IFNs and that the tumor stroma is infiltrated by immune cells, it is conceivable that immune cells provide the source of IFNs, triggering the signal for robust induction of ISG15 in cancer cells." (PMID 36319753, 2022). "WBSCR22 works in concert with TRMT112 to exert a tumor suppressor effect in PC, which negatively mediates translation of the oncogenic factor interferon-stimulated gene 15 (ISG15)." (PMID 35590385, 2022). "Among the ten tumor-related genes used in the risk model, TRIM15, NEK6, ISG15, RFC2, and NR1H3 were upregulated." (PMID 36189312, 2022). "ISG15 is significantly upregulated in PC specimens and favors various malignant phenotypes (rapid cell proliferation, invasion, and tumor formation) of PC." (PMID 35590385, 2022). "ISG15 upregulation in advanced-stage high-grade serous ovarian cancer (HGSOC) leads to an increase in the number of tumor-infiltrating CD8 + lymphocytes, improving median overall survival." (PMID 36319753, 2022). "Knocking down ISG15 with small interfering RNA (siRNA) inhibited xenografted HCC tumor growth and prolonged the lifespan of tumor-bearing mice." (PMID 35159348, 2022). "The genes upregulated in MΦ subtypes from tumours treated with topical caerin gel including Stat2, Isg15, Tap1, Psmb9, and Parp9, were more highly expressed in the CCI than CCII MΦs." (PMID 36497272, 2022). "Depletion of autophagy elongation proteins induces ISG15 expression through STAT1 activation, resulting in the acquisition of tumor-associated phenotypes such as cell proliferation, migration, and invasion." (PMID 36319753, 2022). "The aberrant activation of the ISG15 leads to a higher motility of tumor cells by disrupting cytoskeletal architecture and stabilizing proteins that contributes to cell motility, invasion and metastasis." (PMID 36500393, 2022). "ISG15, also known as interferon-stimulated gene 15, has been reported to be overexpressed in PCa and to promote tumor cell proliferation in previous studies." (PMID 35538543, 2022). "The inhibition of topoisomerase I degradation by ISG15, in turn, confers camptothecin sensitivity to tumor cells." (PMID 35159348, 2022). "By analysis of single-cell RNA sequencing data, MIT score was positively correlated with the proportion of tumor-promoting immune cell clusters, especially the Mac_C1QA, Mac_SPP1 and Mac_ISG15 population." (PMID 35087839, 2021). "ISG15 knockdown cells were subcutaneously injected to mice and the tumor size in wild type mice versus mice carrying ISG15 knockdown cells were compared." (PMID 34781949, 2021).